STAG3L1 (STAG3 cohesin complex component like 1 (pseudogene))
Synonyms: DKFZP434A0131; STAG3L1P
Gene: Transcribed unprocessed pseudogene on chromosome 7 (75,361,374 to 75,367,087, forward strand). Ensembl gene ENSG00000205583.
Subcellular location: Nucleus
Diseases named in the same sentence as STAG3L1 in open-access papers:
STAG3L1 is named in the same sentence as 1 disease in open-access papers, as found by Europe PMC text mining. Sharing a sentence is not in itself a finding about the gene and the disease. The quoted sentences say what the papers report.
autoimmune disease (1 paper, 2010). A disorder resulting from loss of function or tissue destruction of an organ or multiple organs, arising from humoral or cellular immune responses of the individual to their own tissue constituents. "Interestingly, all of the validated transcripts, with the exception of FAM49B and STAG3L1, which are genes encoding proteins of as yet unknown function, have been previously reported to be associated with MS and other autoimmune diseases." (PMID 20126412, 2010).